REV1 (REV1 DNA directed polymerase)
Description:
Bifunctional protein involved in the maintenance of genome stability through translesion DNA synthesis (TLS) and antibody diversification via somatic hypermutation. Functions as a molecular adapter protein at stalled DNA replication, coordinating polymerases recruitment, selection, and switching, in a manner independent of its deoxycytidyl transferase activity. At the site of DNA lesion, recruits and mediates the switch between low-fidelity inserter DNA polymerases, such as POLK, that incorporate nucleotides opposite lesions and the extender DNA polymerase zeta complex which continues DNA synthesis from distorted primer termini. In vitro, acts as a template-dependent deoxycytidyl transferase that preferentially incorporates deoxycytidine residues from dCTP to the 3'-end of a DNA primer opposite apurinic/apyrimidinic (AP) site, uracil, undamaged DNA templates (G > A > C > T) and a variety of damaged DNA templates. Opposite template guanine, efficiently incorporates not only dCMP but also non-complementary dGMP and dTMP, with lower efficiency for dAMP, demonstrating low fidelity on undamaged DNA. This catalytic activity has been implicated in somatic hypermutation, likely achieved by incorporation of deoxycytidine opposite abasic sites, generated at cytidines via activation-induced deoxycytidine deaminase (AID)-mediated deamination and uracil DNA glycosylase (UNG) activity, respectively. In addition, exhibits a 5'-deoxyribose-5-phosphate lyase activity in vitro, though its necessity in vivo is not confirmed (By similarity).
Synonyms: AIBP80; REV1L
Tractability: Small molecule: a structure with a bound ligand is known; a high-quality ligand is known; it has a binding pocket of medium quality. PROTAC: ubiquitination databases record sites on it; a small molecule that binds it is known.
Target class: Enzyme; Transferase
Gene: Protein-coding gene on chromosome 2 (99,400,475 to 99,490,260, reverse strand). Ensembl gene ENSG00000135945.
Subcellular location: Nucleus
Subcellular location (Human Protein Atlas): Nucleoli
Pathways (Reactome):
DNA Repair: Termination of translesion DNA synthesis; Translesion synthesis by POLI; Translesion synthesis by POLK; Translesion synthesis by REV1
Gene Ontology:
Molecular function: deoxycytidyl transferase activity; DNA binding; molecular adaptor activity; protein binding; protein-macromolecule adaptor activity; ubiquitin binding; damaged DNA binding; DNA-(abasic site) binding; DNA polymerase activity; DNA-directed DNA polymerase activity; nucleotidyltransferase activity
Biological process: DNA biosynthetic process; somatic hypermutation of immunoglobulin genes; translesion synthesis; error-free translesion synthesis; error-prone translesion synthesis; DNA repair
Cellular component: nuclear replication fork; nucleolus; nucleus; site of DNA damage; nucleoplasm; site of double-strand break
Genetic constraint (gnomAD): Loss-of-function variants: 26 observed, 100 expected, observed/expected ratio (o/e) 0.26, 90% interval 0.19 to 0.36. The upper end of that interval is the gene's LOEUF score, 0.36, which puts it in group 1 of 6, group 1 being the genes least tolerant of losing a copy. Missense variants: 1,036 observed, 1,221.5 expected, observed/expected ratio (o/e) 0.85, 90% interval 0.81 to 0.89. Synonymous variants: 419 observed, 432.76 expected, observed/expected ratio (o/e) 0.97, 90% interval 0.89 to 1.05.
Homologues: Orthologues: chimpanzee REV1 (99% identical), macaque REV1 (98% identical), dog REV1 (87% identical), pig REV1 (87% identical), guinea pig REV1 (86% identical), rabbit REV1 (86% identical), mouse Rev1 (84% identical), rat Rev1 (82% identical), tropical clawed frog rev1 (65% identical), zebrafish rev1 (51% identical), Drosophila melanogaster Rev1 (28% identical), Caenorhabditis elegans rev-1 (22% identical). Paralogues in human: POLK (14% identical), POLI (11% identical), POLH (11% identical), ESCO1 (7% identical), ESCO2 (6% identical).
Diseases named in the same sentence as REV1 in open-access papers:
REV1 is named in the same sentence as 72 diseases in open-access papers, as found by Europe PMC text mining. Sharing a sentence is not in itself a finding about the gene and the disease. The quoted sentences say what the papers report.
breast carcinoma (10 papers, 2017 to 2025). "Genetic variant rs3792152 of REV1 is associated with breast cancer risk in Thai women and rs2981582 ofFGFR2(Fibroblast Growth Factor Receptor 2) plays a vital role in the cell proliferation, migration, and apoptosis." (PMID 32487238, 2020). "To exclude mouse to human variability with regards to REV1-sensitivity, we knocked down Rev1 with siRNAs in human colorectal and breast cancer cell lines HCT116 and MCF-7, respectively." (PMID 35819193, 2022). "Differential reliance on the polymerase among pathways may help to explain why, e.g., in urothelial tumors carrying missense mutations in ERCC2, a key component of NER, the number of SBS5 mutations increases, while in breast cancer cell lines lacking the TLS polymerase REV1, it decreases." (PMID 40950171, 2025). "When the concentration of ADR is large or the treatment time is longer, the expression of REV1 and FANCF is decreased in breast cancer cells." (PMID 31511498, 2019).
brucellosis (10 papers, 2018 to 2025). Brucellosis is a bacterial infection that spreads from animals to people via unpasteurized dairy products or by exposure to contaminated animal products or infected animals. "Until a more effective vaccine is developed, the Rev1 vaccine remains the preferred vaccine to reduce brucellosis in regions where it is endemic in goats." (PMID 41441675, 2025). "The report of B. melitensis membrane blebs was the first evidence about the use of membrane blebs as a vaccine against brucellosis, which elicited a cellular protective response in mice, similar to that induced by the B. melitensis Rev1 live vaccine." (PMID 31849872, 2019). "In these natural hosts, brucellae display a tropism towards the reproductive organs, such as the placenta, replicating in high numbers and leading to placentitis and abortion, an ability also exerted by the B. melitensis live-attenuated Rev1 strain, the only vaccine available for ovine brucellosis." (PMID 39457012, 2024). "However, Rev1 is virulent in humans, induces abortions when used in pregnant animals and is resistant to streptomycin, an antibiotic of choice for brucellosis treatment." (PMID 31730501, 2019). "Moreover, any tagged vaccine for small ruminant brucellosis would be useful only if its virulence pattern and protection conferred are, at least, equivalent to that of the classical Rev1 vaccine." (PMID 30375177, 2019). "The S19 and Rev1 have been successfully used in many developed countries to control bovine brucellosis, but both vaccines can induce antibodies to B. abortus lipopolysaccharide (LPS) O-side chain that are used in brucellosis serologic diagnosis." (PMID 29867505, 2018). "The recommended dose for brucellosis R vaccines is also 108 CFU/mouse and, like the autoagglutination commented above this suggests surface similarities between the Rev1::Tn7wbdRΔwbkC construct and R brucellae." (PMID 31730501, 2019).
lung carcinoma (9 papers, 2015 to 2025). "Combining the results of in vitro and in vivo experiments, it can be concluded that REV1 inhibition enhances the radiosensitivity of lung cancer cells and that this process is associated with Gly/Ser/Thr metabolism." (PMID 38802791, 2024). "In this study, through a combined transcriptomic and nontargeted metabolomic approach, we found that the initial differential effects of REV1 on lung cancer radiosensitivity in vitro and in vivo were caused by differences in the metabolic microenvironment." (PMID 38802791, 2024). "In the present study, we found that REV1 is abnormally upregulated in patients with lung cancer and that overexpression of REV1 is associated with poor prognosis." (PMID 35115490, 2022). "Our results indicated that REV1 is overexpressed in lung cancer and that high expression of REV1 is associated with poor clinical outcomes in lung cancer patients." (PMID 35115490, 2022). "The activities of REV3 and REV1 have been linked to the drug resistance to cisplatin and cyclophosphamide in murine models of both B-cell lymphoma and lung cancer." (PMID 25781640, 2015). "Importantly, overexpression of REV1 in USP9X-deficient lung cancer cells was able to reverse the upregulation of CTH expression." (PMID 38802791, 2024). "Next, we performed in vitro experiments using conditioned media with depletion of specific amino acids and found that after radiation treatment, REV1-deficient lung cancer cells exhibited extended comet tails, a reduced number of Rad51 foci, and increased radiosensitivity." (PMID 38802791, 2024). "Furthermore, we revealed that the aberrant high expression of REV1 in lung cancer is caused by USP9X-mediated deubiquitination modifications." (PMID 38802791, 2024). "REV1 N373S SNP was associated with an increased risk of cervical cancer, while F257S SNP is associated with a reduced risk of cervical cancer and an increased risk of lung cancer in people with heavy smoking." (PMID 36246647, 2022). "Our study confirmed that REV1 is a potential diagnostic marker and therapeutic target for lung cancer and that JH-RE-06 may be a safe and efficient therapeutic agent for NSCLC." (PMID 35115490, 2022). "Genetic or pharmacological inhibition of REV1 can induce metabolic reprogramming in tumor cells and ultimately reverse radiotherapy resistance in lung cancer." (PMID 38802791, 2024). "A novel inhibitor of REV1, JH-RE-06, was shown to enhance lung cancer cell radiosensitivity, with good prospects for clinical translation." (PMID 38802791, 2024). "We first exogenously overexpressed REV1 in lung cancer cells and detected the downregulation of CTH expression." (PMID 38802791, 2024). "First, stable knockdown of REV1 expression in the A549 lung cancer cell line was achieved using shRNA technology, and a subcutaneous transplantation tumor model was constructed in nude mice." (PMID 38802791, 2024). "To investigate the role of REV1 in lung cancer radiotherapy, we performed radiosensitivity assays in vivo and in vitro." (PMID 38802791, 2024). "Ubiquitination assay results indicated REV1 can be significantly ubiquitinated in lung cancer cells, and the positive regulatory effect of USP9X on REV1 can be reversed by MG132." (PMID 38802791, 2024). "We found that knockdown of REV1 or SERTAD2 markedly suppressed the proliferation of lung cancer cells." (PMID 35115490, 2022). "The heterozygote of REV1 rs3087386 (F257S) and rs3792136 were independent prognostic factors for lung cancer survival with hazard radio (HR) 1.54 (95% CI: 1.12–2.12) and 1.44 (95% CI: 1.06–1.97) respectively." (PMID 36246647, 2022). "Functional experiments demonstrated that REV1 silencing decreased the growth and proliferation capacity of lung cancer cells." (PMID 35115490, 2022). "In this study, we found that the expression of REV1 was significantly upregulated in lung cancer tissues compared with matched adjacent tissues and was associated with poor prognosis." (PMID 35115490, 2022).
lung carcinoma (continued). "Through IHC staining of a lung adenocarcinoma tissue microarray containing 77 pairs of cancerous and paracancerous tissues, we found that the expression of REV1 in lung cancer tissue was significantly higher than that in adjacent tissue." (PMID 35115490, 2022). "A novel small molecule inhibitor of REV1, JH-RE-06, was shown to inhibit the growth and proliferation of lung cancer cells in vivo and in vitro with a manageable safety profile." (PMID 35115490, 2022). "Silencing endogenous REV1 significantly reduced the growth and colony formation ability of lung cancer cells." (PMID 35115490, 2022). "Specifically, the central polymerase in TLS, REV1, is abnormally overexpressed and exerts oncogenic effects in lung cancer." (PMID 35115490, 2022). "Functional experiments suggested that the enhancement of lung cancer cell proliferation induced by REV1 overexpression was reversed by Rad18 deletion." (PMID 35115490, 2022). "Functionally, we demonstrated that inhibition of REV1 can significantly reduce the growth and proliferation of lung cancer cells both in vivo and in vitro." (PMID 35115490, 2022). "The expression of SERTAD2 was significantly downregulated in REV1-silenced A549 and H1299 lung cancer cells." (PMID 35115490, 2022). "The mRNA level of these molecules was detected by real-time quantitative polymerase chain reaction (qPCR) in scrambled and REV1-silenced lung cancer cells." (PMID 35115490, 2022). "Both REV1 silencing and JH-RE-06 treatment can inhibit the growth and proliferation of lung cancer cells in vitro." (PMID 35115490, 2022). "We found that REV1 is highly expressed in lung cancer and that a high expression level of REV1 predicts poor prognosis." (PMID 35115490, 2022). "SERTAD2 partially reversed the decrease in proliferation induced by REV1 silencing in lung cancer cells." (PMID 35115490, 2022). "Functionally, the acceleration of lung cancer cell proliferation induced by overexpression of REV1 was partially reversed by deletion of Rad18." (PMID 35115490, 2022). "As expected, depletion of REV1 significantly decreased the proportion of EdU-positive cells among lung cancer cells, indicating that the proliferation ability of lung cancer cells was substantially impaired." (PMID 35115490, 2022). "Kaplan–Meier (K–M) survival analysis showed that high expression of REV1 predicted a shorter overall survival time in patients with lung cancer." (PMID 35115490, 2022). "In REV1-silenced lung cancer cells, the expression level of SERTAD2 was significantly reduced, and the expression levels of Rad18, mUb-PCNA and RPA32 were also reduced to varying degrees." (PMID 35115490, 2022). "Moreover, both the data from the GEPIA database and the detection of protein expression in lung cancer tissue microarray confirmed that the expression of USP9X was positively correlated with REV1." (PMID 38802791, 2024). "Thus, our study provides a theoretical basis for the clinical translation of the REV1-targeted drug JH-RE-06 and presents a new idea for radiotherapy sensitization in patients with lung cancer." (PMID 38802791, 2024). "Furthermore, knockdown of USP9X in two different lung cancer cell lines resulted in the downregulation of REV1 expression, suggesting positive regulation of REV1 by USP9X." (PMID 38802791, 2024). "Importantly, the rescue assay revealed that CTH expression was downregulated in lung cancer cells overexpressing REV1." (PMID 38802791, 2024). "Thus, our study satisfactorily explains the aberrant expression of REV1 in lung cancer cells, i.e., overexpression of REV1, a newly identified USP9X substrate, is the result of USP9X-mediated deubiquitination." (PMID 38802791, 2024). "This indicates that REV1 can biologically function as an oncogene in lung cancer." (PMID 38802791, 2024). "In addition, JH-RE-06, a novel small-molecule inhibitor of REV1, was shown to enhance lung cancer cell radiosensitivity in vitro and in vivo, with good clinical translation prospects." (PMID 38802791, 2024).
lung carcinoma (continued). "These phenotypes were partially reverted by exogenous overexpression of REV1, suggesting that USP9X could induce radioresistance in lung cancer cells by stabilizing REV1 expression." (PMID 38802791, 2024). "In this study, we report for the first time that the high REV1 expression in lung cancer is associated with the deubiquitinase USP9X and that abnormally high REV1 expression can act as a scaffolding protein to assist the E3 ubiquitin ligase Rad18 binding to the substrate CTH." (PMID 38802791, 2024). "This study aims to clarify the role of REV1 in lung cancer radioresistance, identify the intrinsic mechanisms involved, and provide a theoretical basis for the clinical translation of this new target for lung cancer treatment." (PMID 38802791, 2024). "Given its high expression in lung cancer, we speculated that REV1 may function as an oncogene in the pathogenesis of lung cancer." (PMID 35115490, 2022). "Considering these results collectively, we proposed that SERTAD2 is an oncogene in lung cancer and REV1 may promote lung tumorigenesis by regulating the expression of SERTAD2." (PMID 35115490, 2022). "In summary, our results identified the oncogenic role of REV1 in lung cancer, suggesting that REV1 may constitute a new prognostic marker and therapeutic target for NSCLC." (PMID 35115490, 2022). "In our study, REV1 was revealed to be a novel oncoprotein in lung cancer." (PMID 35115490, 2022). "More importantly, the REV1 inhibitor JH-RE-06 may be an attractive potential antitumor agent due to its inhibitory effects on the proliferation of lung cancer cells and low toxicity in vivo." (PMID 35115490, 2022). "REV1 promotes lung tumorigenesis by activating Rad18/SERTAD2 signaling axis in lung cancer cells." (PMID 35115490, 2022). "Subsequent rescue experiments confirmed our hypothesis that the regulatory effect of REV1 on the proliferation of lung cancer cells is partially dependent on SERTAD2." (PMID 35115490, 2022). "We further evaluated the expression of REV1 in lung cancer and its relationship with prognosis." (PMID 35115490, 2022). "Our previous study found that the expression of REV1 DNA directed polymerase (REV1), a core member of the TLS polymerase family, was significantly upregulated in lung cancer tissues and correlated with poor prognosis." (PMID 38802791, 2024). "To further clarify the role of USP9X-stabilized REV1 expression in lung cancer radioresistance and to elucidate whether this process is associated with alterations in the metabolic microenvironment, we transferred exogenously expressed REV1 into USP9X-deficient lung cancer cells." (PMID 38802791, 2024). "Mechanistically, the ubiquitination compound library screening system identified the USP9X deubiquitinase as a novel upstream REV1 regulatory protein, and that USP9X mediated REV1 deubiquitination modifications to stabilize its expression in lung cancer." (PMID 38802791, 2024). "The central member of the family of TLS polymerases (REV1) upregulates SERTAD2 expressions in a Rad18-dependent manner, thereby enhancing lung cancer development." (PMID 37396042, 2023). "Western blot analysis showed that the expression of REV1, Rad18, RPA32 and REV7 was markedly elevated in several lung cancer cell lines (A549, H1299, Calu-1, and SPC-A1) compared with the normal bronchial epithelial cells HBE." (PMID 35115490, 2022). "Through IHC staining of lung adenocarcinoma and adjacent tissue samples and Western blot analysis of multiple lung cancer cell lines, we found that many important molecules in TLS (REV1, Rad18 and RPA32) were abnormally overexpressed in lung cancer." (PMID 35115490, 2022). "Additionally, in lung cancer cell lines, CTH ubiquitylation by Rad18 and the REV1 scaffolding role were indicated by the effects of ligase silencing, REV1 overexpression, and MG132 addition." (PMID 40141131, 2025).